PKD2L2 (polycystin 2 like 2, transient receptor potential cation channel)
Description:
Exhibits a lower single conductance but no spontaneous channel activity. May function as a regulator of calcium channels or a channel component involving Ca2(+) homeostasis (By similarity).
Synonyms: TRPP5
Tractability: Small molecule: it belongs to a druggable protein family. Antibody: UniProt predicts a signal peptide or a membrane-spanning region; the Human Protein Atlas places it where antibodies can reach. PROTAC: ubiquitination databases record sites on it.
Gene: Protein-coding gene on chromosome 5 (137,887,968 to 137,942,747, forward strand). Ensembl gene ENSG00000078795.
Subcellular location: Membrane
Subcellular location (Human Protein Atlas): Plasma membrane; Cytosol
Gene Ontology:
Molecular function: calcium channel activity; calcium ion binding
Biological process: detection of mechanical stimulus; calcium ion transmembrane transport
Cellular component: membrane
Genetic constraint (gnomAD): Loss-of-function variants: 11 observed, 16.4 expected, observed/expected ratio (o/e) 0.67, 90% interval 0.42 to 1.11. The upper end of that interval is the gene's LOEUF score, 1.11, which puts it in group 4 of 6, group 1 being the genes least tolerant of losing a copy. Missense variants: 147 observed, 173.12 expected, observed/expected ratio (o/e) 0.85, 90% interval 0.74 to 0.97. Synonymous variants: 67 observed, 63.98 expected, observed/expected ratio (o/e) 1.05, 90% interval 0.86 to 1.28.
Homologues: Orthologues: chimpanzee PKD2L2 (99% identical), pig PKD2L2 (88% identical), dog PKD2L2 (88% identical), guinea pig PKD2L2 (86% identical), rabbit PKD2L2 (83% identical), mouse Pkd2l2 (81% identical), rat Pkd2l2 (81% identical), macaque PKD2L2 (52% identical), Caenorhabditis elegans pkd-2 (32% identical), Drosophila melanogaster Pkd2 (30% identical), zebrafish pkd1l2a (23% identical), zebrafish pkd1l2b (21% identical), and 2 more. Paralogues in human: PKD2L1 (47% identical), PKD2 (46% identical), PKDREJ (18% identical), PKD1 (16% identical), LOXHD1 (15% identical), PKD1L1 (15% identical), PKD1L3 (15% identical), DENND5A (12% identical), DENND5B (12% identical), PKD1L2 (10% identical).
Diseases named in the same sentence as PKD2L2 in open-access papers:
PKD2L2 is named in the same sentence as 3 diseases in open-access papers, as found by Europe PMC text mining. Sharing a sentence is not in itself a finding about the gene and the disease. The quoted sentences say what the papers report.
thyroid papillary carcinoma (1 paper, 2021). "Expression of mRNA encoding polycystin 2-like 2 (PKD2L2), which functions to maintain high ciliary Ca2+ concentrations, was significantly downregulated in thyroid papillary carcinoma cells with LOF of primary cilia." (PMID 33602982, 2021).
PKD2L2 also shares sentences with these, for which no sentence is quoted: kidney disease (1 paper); tumor (1).